SOCS1 (suppressor of cytokine signaling 1)
Diseases named in the same sentence as SOCS1 in open-access papers (continued):
Sharing a sentence is not in itself a finding about the gene and the disease.
diabetes (27 papers, 2011 to 2025). "The mechanisms underlying SOCS-1 effects during infection in hyperglycemia/diabetes models are the current focus of our laboratory." (PMID 33690673, 2021). "In the present study, we provide evidence that SOCS1 avoids the increase in retinal glutamate levels and that this is associated with a dramatic inhibition of diabetes induced GLAST downregulation." (PMID 31344857, 2019). "In contrast, IL-21R-deficient 8.3 mice have reduced diabetes incidence and reduced SOCS1 reporter activity in islet CTLs." (PMID 31653894, 2019). "Thus, we found that intrarenal delivery of adenovirus expressing SOCS1 to diabetic rats significantly improved renal function and reduced renal lesions associated with diabetes, such as mesangial expansion, fibrosis, and the influx of macrophages." (PMID 31344857, 2019). "Furthermore, half (3/6) of the buffer-treated SOCS1-tg mice developed diabetes upon infection with CVB1, with a loss of the insulin-positive beta cells and damage to the exocrine pancreas." (PMID 29151123, 2018). "Recently, a highly immunogenic formalin-inactivated CVB1 vaccine has been able to provide protection against acute CVB1 infection in NOD mice and against CVB1-induced diabetes in transgenic SOCS1-tg mice." (PMID 35456818, 2022). "Previous reports have shown that SOCS1 overexpression in NOD mice islets prevent diabetes, and delays allogeneic islet graft rejection in mouse models." (PMID 36055241, 2022). "SOCS1 peptidomimetic treatment was able to prevent the overexpression (mRNA and protein) of IL-1β induced by diabetes." (PMID 31344857, 2019). "In brief, we found that SOCS1-derived peptide significantly reduced glial activation and neural apoptosis induced by diabetes, as well as retinal levels of proinflammatory cytokines." (PMID 31344857, 2019). "Regarding VEGF, SOCS1 peptidomimetic treatment significantly decreased the overexpression of VEGF induced by diabetes." (PMID 31344857, 2019). "SOCS1 reporter activity was examined in the islets of NOD.SOCS1/hCD4 mice during progression to diabetes by immunohistochemistry and flow cytometry." (PMID 31653894, 2019). "Treatment with SOCS1 peptidomimetic was able to ameliorate these functional abnormalities induced by diabetes." (PMID 31344857, 2019). "In contrast, all seven vaccinated SOCS1-tg mice were protected from diabetes and showed normal pancreas morphology on day 21 p.i. with healthy exocrine tissue and intense insulin and glucagon staining in the islets of Langerhans." (PMID 29151123, 2018). "Mice with transgenic expression of suppressor of cytokine signaling 1 (SOCS1) in islets showed markedly reduced incidence of diabetes." (PMID 23671851, 2013). "Therefore, the beta cells succumb to CVB infection, and SOCS-1-tg mice develop diabetes approximately 5–12 days after infection." (PMID 40760251, 2025). "Inhibition of Stat1 was involved in the antioxidant effect of SOCS1 in diabetes." (PMID 31337338, 2019). "For example, it was reported that diabetes-prone NOD mice harboring beta-cells expressing a SOCS1 transgene had a markedly reduced incidence of diabetes, and the disease protection was correlated with enhanced suppression of STAT1 phosphorylation in SOCS1-expressing beta-cells." (PMID 30936880, 2019). "SOCS1-tg mice express the suppressor of cytokine signalling-1 in beta cells, resulting in their inability to respond to interferons, thus leaving beta cells susceptible to CVB infection, destruction and subsequently virus-induced diabetes." (PMID 29151123, 2018). "SOCS1-tg mice, which are susceptible to virus-induced diabetes, showed no adverse changes in weight and blood glucose after CVB1 vaccination (data not shown)." (PMID 29151123, 2018). "In contrast, all (7/7) vaccinated SOCS1-tg mice were protected from virus-induced diabetes and showed no signs of beta cell loss or pancreas destruction (p < 0.05)." (PMID 29151123, 2018).
diabetes (continued). "Approaches to supplement SOC1 or mimic native SOCS1 function may have therapeutic effects on accelerated atherosclerosis in diabetes." (PMID 28883907, 2017). "Another group found that SOCS-1 transgenic islets express less of the IFNγ inducible chemokine Cxcl10 that is usually produced by islets during diabetes development and may be involved in recruitment of autoreactive T cells to the inflamed pancreas." (PMID 27242781, 2016). "Another report found that SOCS-1 overexpression induced by an adenovirus system increased the survival of rat islets transplanted into allogeneic recipients with streptozotocin-induced diabetes." (PMID 27242781, 2016). "Follow-up studies have identified several mechanisms through which SOCS-1 overexpression may improve β-cell survival in diabetes and islet transplantation models." (PMID 27242781, 2016). "Cell internalized SOCS1-KIR is a potent therapeutic in the experimental allergic encephalomyelitis (EAE) mouse model of multiple sclerosis and showed promise in a psoriasis model and a model of diabetes-associated cardiovascular disease." (PMID 25954276, 2015). "This study aimed to evaluate the roles of SOCS-1 and SOCS-3 in the pancreas, liver, and kidney and to explore the involvement of the JAK/STAT pathway in the molecular mechanisms underlying their effects on inflammation and apoptosis, as well as organ injury in a diabetes mellitus (DM) model." (PMID 39968090, 2025). "Thus, the SOCS/JAK/STAT cascade was a key molecular mechanism through which diabetes promoted atherosclerotic plaque formation, and SOCS1 endogenous protein may be a feasible target for modulating inflammation-related complications of diabetes mellitus." (PMID 28883907, 2017). "Importantly, SOCS1-Tg islets significantly reversed STZ-induced diabetes indicating that intragraft expression of SOCS1 rendered islets insensitive to the deleterious effects of cytokines; a finding of potential significance in the development of therapies against acute allograft rejection." (PMID 22046502, 2011). "SOCS1-KIR, when internalized by cells, has shown strong therapeutic potential in EAE, autoimmune uveitis, psoriasis, and diabetes models." (PMID 38022642, 2023). "Regarding the mechanisms involved in the beneficial effect of the SOCS1 peptidomimetic, we found that it reduces the upregulation of IL-1β, IL-6, TNF-α, and VEGF induced by diabetes." (PMID 31344857, 2019). "These include genes with known function in islets and diabetes such as ATP6V1H, SOX6, SOCS1 and STX1145–48." (PMID 31123324, 2019). "CVB3-infected SOCS-1-transgenic (tg) mice were treated with immune- or non-immune sera on days 2 and 3 p.i., followed by monitoring of diabetes development." (PMID 40760251, 2025). "We next conducted the Binary logistic regression analyses to determine the correlation of SOCS1 with ISR, using demographic and clinical characteristics, including diabetes, body mass index, creatinine, total cholesterol, LDL cholesterol, or smoking status as confounders." (PMID 28915645, 2017). "Thus we next tested whether type I IFNs or IL-21 were mediators of the observed SOCS1 induction in islet CD8+ T cells and/or were required for CTL differentiation and diabetes development." (PMID 31653894, 2019).
asthma (26 papers, 2012 to 2024). "Deficiency in SOCS1, a member of the SOCS protein family, has been implicated in lupus, scleritis, and asthma patients, suggesting a role of SOCS1 in the regulation of immune homeostasis." (PMID 33737712, 2021). "A study assessing functional variants of Socs1 within a population of adult Japanese asthma patients found a significant association between the Socs1 promoter polymorphism (−1478CA < del) and adult asthma." (PMID 27917175, 2016). "It is suggested that promoter polymorphism leads to increased SOCS1 and inhibition of interferons, leading to higher susceptibility to virus-induced asthma exacerbations." (PMID 27917175, 2016). "The data from SOCS1-deficient mice in the ovalbumin model of asthma, a Th2-/M2-type disease, support the role of SOCS1 as a negative regulator of M2 polarization." (PMID 26579124, 2015). "Of further note is the occurrence of genetic polymorphism in the SOCS-1 gene where a particularly significant association has been found between asthma susceptibility and a promotor polymorphism (-1478CA) which was shown to cause increased transcription of SOCS-1." (PMID 22970254, 2012). "Thus, there is a potential for gene-gene interactions involving polymorphisms in the TGFΒ2 and SOCS1 genes linked to virus-induced asthma exacerbations." (PMID 22970254, 2012). "Over-expression of miRNA-221-5p induced the protein expression of FOXP3, and suppressed that of SOCS1 and RORγt in in vitro model of asthma." (PMID 34863307, 2021). "Rhy-SLNs mitigated the asthma progression via the upregulation of SOCS1 by suppressing the p38 signaling pathway." (PMID 34629023, 2021). "The inhibition of SOCS1 or RORγt attenuated the effects of anti-miRNA-221-5p on Th17/Treg ratio in asthma." (PMID 34863307, 2021). "Second, it will be more persuasive to rescue the SOCS1 and block the p38 signaling for the mechanism of the anti-asthma effects of Rhy-SLNs." (PMID 34629023, 2021). "In patients with severe asthma, decreased SOCS1 expression correlated with eosinophilia and Th2-driven inflammation." (PMID 34421895, 2021). "In this work, we found that Rhy-SLNs significantly elevated the protein levels of SOCS1 of lung tissues in experimental asthma." (PMID 34629023, 2021). "There have been several publications linking SOCS1 expression with allergic diseases such as asthma." (PMID 27917175, 2016). "The increased SOCS1 protein levels correlated with clinical markers of asthma (PC20) and also numbers of positive skin prick test responses, suggesting a relationship between SOCS1 expression and AA." (PMID 25630941, 2015). "We describe a novel mechanism explaining interferon deficiency in asthmatic patients through a novel nuclear function of SOCS1 and identify SOCS1 as an important therapeutic target for asthma exacerbations." (PMID 25630941, 2015). "We report induction of SOCS1 in bronchial epithelial cells (BECs) by asthma exacerbation–related cytokines and by rhinovirus infection in vitro." (PMID 25630941, 2015). "GSEA analysis showed significant differences between different expression groups of HSPB1 in autophagy, asthma, and glutathione metabolism signaling pathways, and different expression groups of SOCS1 in autophagy and folate biosynthesis signaling pathways, etc.." (PMID 36969832, 2023). "In addition, mir-221 reduced the Th17 cell function by directly inhibiting RORγt/SOCS1 and promoted the function of Treg cells via induction of Foxp3/SOCS1 in asthma." (PMID 36172292, 2022). "Based on the results of Rhy-SLNs on OVA-induced inflammation, we speculated that SOCS1 might play a role in the anti-asthma function of Rhy-SLNs." (PMID 34629023, 2021). "The inhibition of SOCS1 reduced the effects of anti-miRNA-221-5p on Th17/Treg Ratio in asthma." (PMID 34863307, 2021). "SOCS1 is a negative regulator of IL-4-dependent pathway, resulting in the regulation of IgE, IL-4 and IL-13 levels, as well as the eosinophilic mucosal inflammation in asthma." (PMID 34629023, 2021).
asthma (continued). "In combined with the results of Rhy-SLNs on OVA-induced airway inflammation, we concluded that the protective role of Rhy-SLNs against asthma might be meditated by the upregulation of SOCS1." (PMID 34629023, 2021). "In patients with Henoch-Schönlein purpura (HSP) or asthma, methylation-based silencing of the related genes (e.g., Foxp3, suppressor of cytokine signaling 1 (SOCS1), and SOCS3) disturbed the Treg/Th17 cell balance and critically contributed to pathogenesis of related diseases." (PMID 34239942, 2021). "miRNA-221-5p may play critical roles in driving the differentiation of Th17/Treg ratio via RORγt/Foxp3 by Targeting SOCS1, reduced the function of Th17 cells by directly inhibiting RORγt/SOCS1 and promoted the function of Treg cells via Foxp3/ SOCS1 in asthma." (PMID 34863307, 2021). "Thus we describe a novel mechanism explaining interferon deficiency in asthmatic patients, a new nuclear function of SOCS1, and identify SOCS1 as an important therapeutic target for asthma exacerbations." (PMID 25630941, 2015). "We found that SOCS1 was increased in vivo in bronchial epithelium and related to asthma severity." (PMID 25630941, 2015). "Having excess SOCS1 in BECs could be doubly deleterious in patients with asthma exacerbations in that beneficial antiviral pathways mediated by interferons are suppressed and harmful proinflammatory responses are augmented." (PMID 25630941, 2015). "At this point, we cannot definitively conclude whether SOCS1 expression is increased because of asthma, atopy, or both." (PMID 25630941, 2015). "SOCS1 levels were also correlated with asthma-related clinical outcomes." (PMID 25630941, 2015). "In addition, SOCS1 may also affect the differentiation and function of Th17 through miRNA155 in asthma and systemic sclerosis." (PMID 38006062, 2023). "In conclusion, miRNA-221-5p may play critical roles in driving the differentiation of Th17/Treg ratio via RORγt/Foxp3 by Targeting SOCS1, reduced the function of Th17 cells by directly inhibiting RORγt/SOCS1 and promoted the function of Treg cells via Foxp3/ SOCS1 in asthma." (PMID 34863307, 2021). "Furthermore, because our study numbers remain small, there is a need for further studies with larger patient numbers to confirm whether SOCS1 expression is related to clinical markers of asthma or atopy." (PMID 25630941, 2015). "Also, several inflammatory mediators, of potential relevance to asthma, such as SOCS1, IL1B, IL13RA1 and CCL26 could be potentially affected, directly or indirectly by one or more microRNAs of this list." (PMID 25360780, 2014). "miRNA-221-5p mimics suppressed protein expression of Foxp3 via promoting that of suppressor of cytokine signaling 1 (SOCS1) and receptor-related orphan receptor-gamma-t (RORγt) in mouse model of asthma." (PMID 38632598, 2024). "Alveolar macrophage-derived EVs containing SOCS1 and SOCS3 can inhibit asthma pathogenesis when taken up by AECs." (PMID 36316787, 2022). "The administration of si-SOCS1 suppressed the protein expression of SOCS1 and RORγt and induced that of FOXP3 in in vitro model of asthma following anti-miRNA-221-5p, in comparison with anti-miRNA-221-5p group." (PMID 34863307, 2021). "Over-expression of miRNA-221-5p suppressed the protein expression of SOCS1 and RORγt and induced that of Foxp3 in in vitro model of asthma, compared with negative group." (PMID 34863307, 2021). "In addition, down-regulation of miRNA-221-5p induced the protein expression of suppressor of cytokine signaling 1 (SOCS1) and receptor-related orphan receptor-gamma-t (RORγt) and suppressed that of FOXP3 in in vitro model of asthma." (PMID 34863307, 2021). "Down-regulation of miRNA-221-5p induced the protein expression of SOCS1 and RORγt and suppressed that of Foxp3 in in vitro model of asthma, in comparison with negative group." (PMID 34863307, 2021). "Over-expression of miRNA-221-5p suppressed the protein expression of SOCS1 in in vitro model of asthma, in comparison with negative group." (PMID 34863307, 2021).
asthma (continued). "Polymorphisms in SOCS1 that cause non-functioning or low functioning SOCS1 are a risk factor for MS, SLE, and asthma." (PMID 26579124, 2015). "The inhibition of SOCS1 attenuated the effects of anti-miRNA-221-5p on the increased levels of IL-6, IL-17, IL-21 and IL-22, and suppressed levels of IL-10, IL-35 and TGF-β in in vitro model of asthma following anti-miRNA-221-5p, compared with anti-miRNA-221-5p group." (PMID 34863307, 2021). "Therefore, the effects of RORγt and SOCS1/3 acutely exacerbated RSV infection of asthma Our findings confirmed that Over-expression of miRNA-221-5p suppressed SOCS1 and RORγt protein expression and induced Foxp3 protein expression in vitro model of asthma." (PMID 34863307, 2021). "SOCS1, but not SOCS3, mRNA expression levels were increased (approximately 8- to 9-fold) in unstimulated and uninfected primary human BECs from children with severe asthma compared with those in BECs from NANA control subjects." (PMID 25630941, 2015).